ANKRD60 (ankyrin repeat domain 60)
Synonyms: C20orf86; bA196N14.3
Tractability: No criterion of Open Targets' tractability assessment is met for any kind of drug.
Gene: Protein-coding gene on chromosome 20 (58,216,126 to 58,228,653, reverse strand). Ensembl gene ENSG00000124227.
Genetic constraint (gnomAD): Loss-of-function variants: 22 observed, 19.47 expected, observed/expected ratio (o/e) 1.13, 90% interval 0.81 to 1.61. The upper end of that interval is the gene's LOEUF score, 1.61, which puts it in group 6 of 6, group 1 being the genes least tolerant of losing a copy. Missense variants: 442 observed, 416.14 expected, observed/expected ratio (o/e) 1.06, 90% interval 0.98 to 1.15. Synonymous variants: 165 observed, 172.61 expected, observed/expected ratio (o/e) 0.96, 90% interval 0.84 to 1.09.
Homologues: Orthologues: chimpanzee ANKRD60 (99% identical), macaque ANKRD60 (90% identical), rat Ankrd60 (61% identical), mouse Ankrd60 (59% identical), pig ANKRD60 (48% identical), guinea pig Ankrd60 (35% identical), tropical clawed frog ankrd60 (23% identical).
Diseases named in the same sentence as ANKRD60 in open-access papers:
ANKRD60 is named in the same sentence as 2 diseases in open-access papers, as found by Europe PMC text mining. Sharing a sentence is not in itself a finding about the gene and the disease. The quoted sentences say what the papers report.
adolescent idiopathic scoliosis (1 paper, 2021). A scoliosis with no known cause arising in adolescent. "The detected QTL for the trait back and croup harbors the genes C22H20orf85 and ANKRD60, both of which are potentially linked to adolescent idiopathic scoliosis (AIS) in humans." (PMID 33853519, 2021). "C20orf85 and ANKRD60 are potentially linked to adolescent idiopathic scoliosis in humans." (PMID 33853519, 2021).
ANKRD60 also shares sentences with these, for which no sentence is quoted: cancer (1 paper).